EGFR (epidermal growth factor receptor)
Diseases named in the same sentence as EGFR in open-access papers (continued):
Sharing a sentence is not in itself a finding about the gene and the disease.
cancer (continued). "The acquired resistance to EGFR-TKI in intrinsic sensitive cancer cells correlated with spontaneous loss of E-cadherin, whereas the ectopic expression of E-cadherin sensitized drug-resistant cells to EGFR-TKI, accounting for a direct implication of E-cadherin in ensuing EGFR-TKI resistance." (PMID 40149313, 2025). "Currently, no guidelines recommend this combination in patients with EGFR-mutated carcinoma." (PMID 40364160, 2025). "Survival maps from the GEPIA2 database showed that among the 33 analyzed cancer types, increased expressions of ADAMTS1, L1CAM, and EGFR were only significantly associated with poor survival in HNSCC, implying the critical and specific role of the ADAMTS1-L1CAM-EGFR axis in HNSCC progression." (PMID 38263290, 2024). "Furthermore, Spautin-1 inhibits the EGFR signaling pathway, which contributes to a reduced survival rate of cancer cells, positioning this molecule as a promising candidate for potential cancer therapies." (PMID 39458996, 2024). "Further work will be needed to fully elucidate the role of ADAMTSs in controlling EGF bioavailability and downstream signalling in different cancer types and to establish whether this could lead to novel therapeutic strategies to prevent EGFR-driven tumorigenesis." (PMID 38948119, 2024). "Thus, Def appears to effectively disrupt processes central to cancer progression, such as metastasis and chemoresistance, potentially through its multifaceted impact on EGFR, ABCB1, and NDRG1 pathways, in support of our initial hypothesis." (PMID 39457585, 2024). "Therefore, EGFR is an important target for cancer treatment." (PMID 39358807, 2024). "Thus, this tyrosine-kinase receptor converges with EGFR and its overactivation mimics that of EGFR, being it a well-documented mechanism for bypassing its blockade and promoting cetuximab resistance across various cancer types, including HNSCC, NSCLC, or CRC." (PMID 38467828, 2024). "However, beyond EGFR, the initially resected six tumors have no shared somatic mutations, consistent with their independent origin in the setting of cancer predisposition." (PMID 39406916, 2024). "Notably, although anti-AREG therapy has been considered a possible therapeutic strategy in cancer treatment, the competing concept indicates that EGFR-targeting therapy might still be the predominant developing direction." (PMID 39452130, 2024). "The present study investigated the efficacy of EGFR inhibiting compound 1e, using in‐vitro and in‐vivo methods, in potentiating doxorubicin‐mediated reduced tumorigenesis by sensitization of the breast CSCs toward chemotherapeutic to prevent the relapse of cancer." (PMID 38522013, 2024). "Third-generation EGFR inhibitors, represented by Osimertinib, have saved the lives of countless cancer patients and have been approved by major regulatory agencies for the treatment of EGFR T790M-positive cancer, However, Osimertinib resistance is surfacing as treatment is rolled out." (PMID 39404930, 2024). "Of the patients who received prior anti-cancer treatment, chemotherapy and chemo-immunotherapy were the most commonly used regimens (each used in 27.3%, n = 9/33), followed by tyrosine kinase inhibitors (18.2%, n = 6/33; including half of these patients who received EGFR tyrosine kinase inhibitors)." (PMID 39594790, 2024). "This cohort study of 22 101 patients with NSCLC found that increased targeted therapy use for patients with nonsquamous cancer with EGFR sequence variants or ALK rearrangement in period 2 (2017-2019) was associated with better OS than for similar patients in period 1 (2014-2016)." (PMID 38334998, 2024).
cancer (continued). "Therefore, Zhang Ming believes that exosomes containing EGFR from cancer cells may promote the development of liver-like microenvironment and facilitate liver-specific metastasis." (PMID 39703839, 2024). "Similarly, another recent study by the same research team suggested that genetically engineered exosomes armed with not only CD3, EGFR but also the programmed death 1 and OX40 ligand (OX40L) obviously killed the EGFR-positive cancer cells and inhibited progression of established tumors." (PMID 39698409, 2024). "The primary outcome measure is the fatigue score associated with EGFR-TKI adverse reactions at week 8, evaluated by the Chinese version of the European Organization for Research and Treatment of Cancer (EORTC) Quality of Life Questionnaire for Cancer Patients (QLQ-C30)." (PMID 38500118, 2024). "Another investigation revealed that a ruthenium-based radiosensitizer, combined with 111In-labeled polymeric nanoparticles, may induce combinational and targeted therapeutic effects on cancer cells overexpressing the human epidermal growth factor receptor (EGFR)." (PMID 38560384, 2024). "Pharmacological antagonists of some of these transforming genes (e.g., EGFR inhibitors) could reduce TF expression, both locally and systemically, and these targeted agents are considered as potential indirect and cancer-specific anticoagulants, in addition to their direct antitumor effects." (PMID 38719932, 2024). "Further analysis revealed that adenocarcinoma had a strong association with the expression of Exon 19 deletion mutation in EGFR-positive patients (p=0.04), but the gender, smoking status, occupational exposure, and family history of any cancer did not exhibit any significant association." (PMID 39429333, 2024). "One patient with an EGFR mutation received neoadjuvant osimertinib as bridging therapy before concurrent chemo-RT while completing treatment for a non-lung synchronous primary cancer." (PMID 40462887, 2024). "To model EGFR variant functionality, we employed the PC9 cell line, as it is EGFR-dependent, sensitive to all generations of EGFR TKIs, and amenable to high-throughput genetic screening, while also providing the complexity associated with naturally occurring passenger mutations in cancer." (PMID 38548752, 2024). "The activity and selectivity of BA against cancer cells expressing EGFR were assessed in a panel of cell lines, including NSCLC cell lines harboring either the EGFRL858/T790M double mutation (H1975 cells) or EGFRexon19del (PC-9 and H827 cells) and two cell lines expressing wt-EGFR (A549 and H1299)." (PMID 38764025, 2024). "In addition, alterations in FUTs’ mRNA expressions result in changes in the levels of Lewis antigen abundance, which interfere with various well-known cancer-associated signaling pathways including the PI3K/Akt and EGFR/mitogen-activated protein kinase (MAPK) pathways." (PMID 39123480, 2024). "However, clinical application of the EGFR-neutralizing drug cetuximab has shown that AREG expression/secretion levels can compensatorily increase in the patient’s cancer microenvironment, leading to drug resistance development and being a predictive marker for anti-EGFR treatment." (PMID 39452130, 2024). "Therefore, STAP-2 inhibition can be developed as a therapeutic strategy for EGFR-related cancers." (PMID 38745775, 2024). "Additionally, EGFR-positive cancer patients revealed prolonged progression-free survival after receiving gefitinib treatment compared to patients who do not harbour EGFR gene mutations." (PMID 39410578, 2024). "Additionally, its role in modulating EGFR‐mutated cancer cell sensitivity to TKIs has not been explored previously." (PMID 39435643, 2024).
cancer (continued). "Similarly, genes coding for multiple cytokines and surface protein markers that are known to be associated with the basal phenotype, pluripotency, and cancer aggression, such as CD44, KIT, EGFR, and PROM1, were also significantly upregulated in the BORGHigh tumors." (PMID 39335212, 2024). "Furthermore, we found increased expression of EMT markers, including N-cadherin (CDH2), vimentin (VIM) and Snail (SNAL1), suggesting that B7-H3 may enhance the EGFR-ERK signaling pathway for cancer cell growth and metastasis." (PMID 38370387, 2024). "However, EGFR/HER2 heterodimers are also important targets for antilung cancer therapy." (PMID 39780846, 2024). "A cancer treatment might also be developed by inhibition of epidermal growth factor receptor (EGFR) by competitive binding to inhibit the association of its cytoplasmic juxtamembrane (JM) domain, which is essential for receptor dimerization and kinase function." (PMID 38545547, 2024). "Therefore, inhibition of the interaction between STAP-2 and BRK/EGFR may be a possible therapeutic strategy for these cancers." (PMID 38745775, 2024). "Another reason could be the impact of cancer treatment after EGFR-TKI therapy." (PMID 39156250, 2024). "Therefore, it is possible that the decline of epidermal EGFR-mediated STAT3 signaling switches the balance in favor of STAT1 activation as it is described for STAT3 knockout conditions in various model systems including cancer cells." (PMID 39521937, 2024). "Moreover, it was also shown that integrin α5β1 may facilitate cancer cell invasion and enhance EGFR signaling." (PMID 38177190, 2024). "Thus, CAFs may protect cancer cells by activating other tyrosine kinase receptor-mediated signaling, thereby bypassing the need for EGFR signaling." (PMID 39834587, 2024). "Moreover, various studies have suggested that a dual strategy, targeting both VEGFR and EGFR by combination therapy, may be a promising approach in cancer treatment." (PMID 38158791, 2024). "Near-infrared photoimmunotherapy (NIR-PIT) is a recently developed targeted molecular cancer therapy that combines a target-specific photosensitizer based on the infrared phthalocyanine dye IR700 with a monoclonal antibody against epidermal growth factor receptor (EGFR)." (PMID 38515576, 2024). "Consequently, EGFR is regarded as a promising target for cancer therapy." (PMID 39519855, 2024). "Human EGFR inhibition could slow down or stop the growth of cancer cells." (PMID 38266021, 2024). "Furthermore, there are no currently approved therapeutic options for cancers with EGFR variants located outside of the kinase domain." (PMID 38548752, 2024). "Consequently, cancer-specific EGFR vaccines may be more efficient to produce than a pan-cancer vaccine." (PMID 38675381, 2024). "This discovery establishes a connection between two fundamental signaling pathways, EGFR and WNT, at the level of cytoplasmic membrane receptors, uncovering a novel mechanism underlying the frequent co-activation of EGFR and WNT signaling in development and cancer." (PMID 38260423, 2024). "EGFR not only participates in the differentiation and proliferation of cancer cells, promotes the apoptosis of cancer cells, but also participates in the formation of new blood vessels in cancer tissues, and is closely related to the growth and metastasis of cancer cells." (PMID 38396128, 2024). "In this regard, an insufficient and/or heterogeneous exposure of cancer cells to effective EGFR-TKI levels might promote the emergence of resistance with molecular mechanisms different from those induced when cancer cells are exposed to optimal doses of the drug." (PMID 38732063, 2024). "Notably, the AhR-driven modulation of EGFR function has been investigated in various cancers." (PMID 39211042, 2024). "Notably, TAP levels are elevated in cancer patients, particularly in those at advanced stages and grades, but prior studies did not specifically investigate its association with EGFR mutation in advanced NSCLC." (PMID 38980474, 2024).
cancer (continued). "Mutations and dysregulations of critical RTKs like epidermal growth factor receptor (EGFR), Src kinases, and Numb-associated kinases (NAKs) play a significant role in cell signaling pathways, and their inhibition has been proven to be effective in combating various cancer types." (PMID 39683709, 2024). "Additionally, compounds such as caffeic acid, CAPE, gallic acid, ferulic acid, and tannic acid have shown potential in targeting RTKs for cancer treatment, exhibiting significant effects in inhibiting the EGFR, VEGFR, and PDGFR signaling pathways (see review paper)." (PMID 39519572, 2024). "In some cases, even a change in EGFR levels alone may be sufficient to induce cancer development." (PMID 38324801, 2024). "It is intriguing to speculate that similar mechanisms of IP preservation in HFSCs, identified in this study, are also active in various EGFR-dependent solid tumors and that EGFR inhibition renders them more immunogenic, thereby supporting anti-cancer therapy efficiency." (PMID 39521937, 2024). "Consequently, EGFR/AKT/mTOR inhibitors have attracted considerable attention in cancer research." (PMID 38434350, 2024). "However, in these cases, pulmonary toxicity could be due to MKIs’ peculiar mechanism of action (i.e. epidermal growth factor receptor inhibition on type II pneumocytes), but also directly due to cancer (i.e. paraneoplastic syndrome)." (PMID 39136571, 2024). "Therefore, it should be obvious that EGFR is important for the development of cancer." (PMID 39574469, 2024). "In addition, PGE2-induced EGFR activation, through different EP receptors, may be responsible for the development of resistance to anti-EGFR therapies in some cancer patients." (PMID 37190301, 2023). "One may wonder why EGFR should be considered as a choice of cancer therapy." (PMID 38090376, 2023). "Therefore, the development of possible approaches for increasing synergistic growth inhibition with anti-EGFR therapy for cancer cells may provide tractable therapeutic opportunities for future drug development initiatives." (PMID 37937641, 2023). "Nevertheless, our NGS results were not ideal to elucidate whether the compound EGFR mutations were from the same cancer cell/DNA allele or not." (PMID 36829178, 2023). "Importantly, CD47 blockade significantly enhances EGFR‐targeted cancer therapy in an animal model." (PMID 37541303, 2023). "Similarly, GREM1 can also promote invasion of cancer cells by activating the EGFR pathway." (PMID 37333824, 2023). "Importantly, CD47 blockade enhanced EGFR‐targeted cancer therapy." (PMID 37541303, 2023). "As EGF receptor, Vav1, RhoA, Rac1, and BPGAP1 are all associated with oncogenesis and/or cancer metastasis, the identification of this novel EGFR-BPGAP1-Vav1-Rac1-RhoA signaling axis could provide new approaches to a combinatorial therapeutic intervention in cancer progression." (PMID 36598812, 2023). "As abnormal expression and activation of AXL may promote chemotherapy resistance, cancer cell proliferation, invasion, and metastasis, blocking AXL pathways may enhance the sensitivity of cancer cells to cytotoxic agents and help to overcome the problem of resistance to EGFR TKIs." (PMID 36892745, 2023). "Oncogenic signaling pathways, including B-Raf kinase (BRAF) and epidermal growth factor receptor (EGFR), drive dysregulation of fatty acid metabolism, affecting membrane composition and saturation to regulate tolerance to reactive oxygen species (ROS) and cancer cell survival." (PMID 38025761, 2023).
cancer (continued). "In addition, we observed, that in HMVII cell line treated with foretinib as monotherapy, the pEGFR/EGFR ratio was increased, which may indicate that cancer cells compensate for the decreased pMET/MET ratio by increasing the pEGFR/EGFR ratio." (PMID 37679999, 2023). "Therefore, EGFR is the target of several cancer therapeutics." (PMID 37170144, 2023). "Thus, we further examined the contributions of PELI1 to aberrant EGFR signaling in cancers." (PMID 36841821, 2023). "Nevertheless, in other types of cancers such as OS, these EGFR mutations are extremely rare and it is not yet elucidated whether they are significant in clinical settings." (PMID 37441462, 2023). "Therefore, the development of dual EGFR/BRAF inhibitors is a promising approach in cancer therapy." (PMID 37240450, 2023). "Notably, in this report, we use both EGFR wild type and EGFR mutant cancer cell lines." (PMID 37441599, 2023). "For patients with acquired resistance to EGFR TKIs caused by upregulation or amplification of MET, it may be beneficial to treat with a combination of inhibitors of both MET and EGFR, as this has been shown to have a synergistic inhibitory effect on the proliferation of cancer cells." (PMID 37568643, 2023). "However, targeted EGFR therapy has shown limited clinical success in cancer patients." (PMID 37114127, 2023). "However, the relationship between EGFR mutations and Gefitinib target genes (FBP1, SBK1, and AURKA) warrants further investigation, and cancer tissues were collected to confirm the relationship between the risk model and nomogram and the prognosis of LUAD patients in the future." (PMID 37737707, 2023). "In addition to the genetic mutation status, upregulation of EGFR expression has been identified as a negative prognostic marker for the patient survival in NSCLC cancers." (PMID 37178919, 2023). "We also browsed the PubMed library for articles typed in meta-analysis to clarify whether EGFR mutation serves as a prognostic biomarker for recurrence in other cancers, but no results were obtained." (PMID 37907475, 2023). "Additionally, EGFR is significant in the functioning of certain cancers." (PMID 37046844, 2023). "Targeting ALK and EGFR simultaneously may be an effective way to treat these cancer patients." (PMID 36903251, 2023). "Indeed, RB1 inactivation has been linked to cancer initiation and progression and resistance to several targeted therapies, including androgen receptor (AR) antagonists, ER antagonists, CDK4/6 inhibitors, and EGFR tyrosine kinase inhibitors." (PMID 36928314, 2023). "Damage to the EGFR signaling pathways promotes the inactivation of Bim sensor protein phosphorylation, which leads to the disintegration of the cytoskeleton, followed by the detachment of cancer cells from the extracellular matrix, and, ultimately, to cancer cell death." (PMID 37754201, 2023). "Our findings may be relevant for cancer resistance to anti-EGFR therapy." (PMID 37756411, 2023). "Therefore, EGFR has been considered as an important target for cancer therapy." (PMID 37489364, 2023). "However, EGFR mutated, and non-mutated cancer cells can concurrently exist in a considerable proportion of NSCLC, leading to the heterogeneity of NSCLC cells which results in a reduced response to gefitinib." (PMID 36681071, 2023). "We therefore scrutinized the chemical composition of Momordica charantia (enriched in Momordin Ic) and pinned our hope on the Gallic Acid found in it, as the literature survey showed that it could target major cancer survival players such as EGFR, MAPK, autophagy effectors, glycolysis, etc.." (PMID 36980166, 2023).